LRRC15 (leucine rich repeat containing 15)
Description:
(Microbial infection) Modulates the ability of SARS-CoV-2 to infect host cells through interaction with the spike protein. Does not act as a SARS-CoV-2 entry receptor but sequesters virions and antagonizes in trans SARS-CoV-2 infection of ACE2(+) cells when expressed on nearby cells.
Synonyms: LIB
Tractability: Antibody: UniProt places it where antibodies can reach, with high confidence; its Gene Ontology location is reachable by antibodies, with high confidence; UniProt predicts a signal peptide or a membrane-spanning region; the Human Protein Atlas places it where antibodies can reach.
Gene: Protein-coding gene on chromosome 3 (194,355,249 to 194,369,743, reverse strand). Ensembl gene ENSG00000172061.
Subcellular location: Cell membrane
Subcellular location (Human Protein Atlas): Vesicles; Plasma membrane
Gene Ontology:
Molecular function: collagen binding; fibronectin binding; laminin binding; protein binding; protein sequestering activity; signaling receptor activity
Biological process: host-mediated suppression of symbiont invasion; negative regulation of protein localization to plasma membrane; positive regulation of cell migration; receptor-mediated virion attachment to host cell; positive regulation of synapse assembly
Cellular component: apical plasma membrane; extracellular exosome; plasma membrane
Genetic constraint (gnomAD): Loss-of-function variants: 8 observed, 7.05 expected, observed/expected ratio (o/e) 1.13, 90% interval 0.66 to 1.82. That is too few expected variants to judge how well the gene tolerates losing a copy. Missense variants: 769 observed, 769.27 expected, observed/expected ratio (o/e) 1, 90% interval 0.94 to 1.06. Synonymous variants: 337 observed, 333.83 expected, observed/expected ratio (o/e) 1.01, 90% interval 0.92 to 1.11.
Homologues: Orthologues: chimpanzee LRRC15 (99% identical), macaque LRRC15 (98% identical), dog LRRC15 (91% identical), rabbit LRRC15 (90% identical), pig LRRC15 (88% identical), guinea pig LRRC15 (85% identical), rat Lrrc15 (83% identical), mouse Lrrc15 (82% identical). Paralogues in human: FLRT2 (23% identical), PODN (23% identical), FLRT3 (23% identical), FLRT1 (22% identical), PODNL1 (22% identical), LRRC4 (19% identical), LRRC4C (19% identical), NYX (18% identical), RTN4RL2 (18% identical), LRRTM3 (18% identical), LRRTM4 (18% identical), RTN4RL1 (17% identical), and 10 more.
Diseases named in the same sentence as LRRC15 in open-access papers:
LRRC15 is named in the same sentence as 66 diseases in open-access papers, as found by Europe PMC text mining. Sharing a sentence is not in itself a finding about the gene and the disease. The quoted sentences say what the papers report.
pancreatic cancer (18 papers, 2019 to 2025). "Alternative approaches of annotating CAF populations in pancreatic tumours have also been described, including a population of immune-suppressive Lrrc15+ myofibroblasts, and Endoglin (Eng, encoding CD105) positive and negative CAFs, with the latter associated with anti-tumour immunity." (PMID 38678021, 2024). "Here in mouse models of pancreatic cancer, we provide in vivo genetic evidence that TGFβ receptor type 2 signalling in healthy dermatopontin+ universal fibroblasts is essential for the development of cancer-associated LRRC15+ myofibroblasts." (PMID 36171287, 2022). "LRRC15 has emerged as a marker for cancer-associated fibroblasts, and numerous studies have demonstrated its high expression in various solid tumor types, including triple-negative breast cancer, head and neck cancer, non-small-cell lung cancer, pancreatic cancer, ovarian cancer, and osteosarcoma." (PMID 38611080, 2024). "F5 also demonstrated strong similarity to published myCAF signatures, including Elyada myCAF and LRRC15+ fibroblasts from pancreatic cancer, pan-cancer C10_COMP+ CAF, ECM/TGFβ myCAF from breast cancer and Liu myCAF from PCa." (PMID 41378308, 2025). "CD34– myCAFs express high levels of Lrrc15+, a marker of immunosuppressive fibroblasts that mediates resistance to immune checkpoint blockade in pancreatic cancer, and Col12a1, identified as a potential driver of invasion in breast cancer." (PMID 40216939, 2025). "Of note, pancreatic adenocarcinoma signaling was also highly up-regulated, and this is in line with a recent study highlighting the role of LRRC15+ fibroblasts in driving disease severity in pancreatic cancer." (PMID 36757924, 2023). "Similar to the subcutaneous tumours, ablation of LRRC15+ CAFs in orthotopic pancreatic tumours significantly improved tumour control and synergized with anti-PDL1 to further reduce tumour burden." (PMID 36171287, 2022). "Together, these findings show that therapeutic depletion of LRRC15+ CAFs from the pancreatic tumour microenvironment leads to markedly improved responsiveness to anti-PDL1 ICB treatment." (PMID 36171287, 2022). "In pancreatic cancer, leucine-rich repeat-containing 15 (LRRC15) positive CAFs, induced by TGFβ, have been associated with inferior survival upon ICB." (PMID 36077813, 2022). "Leucine-rich repeat containing 15 (LRRC15) is expressed on CAFs in many solid cancers including pancreatic cancer as well as on a subset of cancer cells of mesenchymal origin." (PMID 33572223, 2021). "A LRRC15-positive CAF subpopulation was identified in a pancreatic cancer mouse model (Pdx1-Cre; lox-stop-lox-KrasG12D/+; p16/p19lox/lox)." (PMID 33572223, 2021). "A recent study identified a leucine-rich repeat containing 15 (LRRC15)-positive CAF subpopulation within the PDPN-positive CAF population in pancreatic cancer mouse model (Pdx1-Cre; lox-stop-lox-KrasG12D/+; p16/p19lox/lox)." (PMID 33333727, 2020). "We discovered that the spatial distributions of Fb_LRRC15, which represents the myCAF population, were highly correlated with pancreatic cancer cell distributions, whereas Fb_SFRP1 cells, representing iCAF, were located distal to the cancer spots, as can be expected from previous studies." (PMID 38297291, 2024). "Further investigations could reveal that leucine-rich-repeat-containing protein 15-positive CAFs (LRRC15) represent the main part of CAFs in pancreatic cancer." (PMID 37686288, 2023). "The trend of high LRRC15+ CAF levels in pancreatic cancer was confirmed in an independent dataset." (PMID 36171287, 2022). "Similar to subcutaneous KPR tumours, development of LRRC15+PDPN+ CAFs in orthotopic pancreatic tumours was significantly impaired in Dptki/kiTgfbr2fl/fl mice compared with control Dptwt/wtTgfbr2fl/fl mice, whereas the total number of PDPN+CD31– fibroblasts remained unchanged." (PMID 36171287, 2022). "The LRRC15-positive CAF subpopulation can be identified in pancreatic cancer patient specimens." (PMID 33333727, 2020).
pancreatic cancer (continued). "Leucine-rich repeat-containing protein 15 (LRRC15) marks TGF-β–responsive CAFs enriched in matrix remodeling and immune suppression, particularly in lung, breast, and pancreatic tumors." (PMID 41441395, 2025). "Among the indications analysed, pancreatic cancer and bladder cancer samples had the highest PC1 values, which indicated strong enrichment of LRRC15+ CAFs." (PMID 36171287, 2022). "Furthermore, DTR+ pancreatic tumours, whether treated with anti-PDL1 or isotype control, showed a near complete ablation of LRRC15+ CAFs and a significant reduction in the total PDPN+ fibroblast compartment." (PMID 36171287, 2022).
breast carcinoma (15 papers, 2019 to 2025). "The data above indicated that COL10A1 could be associated with the LRRC15 signaling pathways in breast cancer." (PMID 32043519, 2020). "In breast cancer, LRRC15 promotes the migration and invasion of triple-negative breast cancer (TNBC) cells via the Wnt/β-catenin signaling pathway." (PMID 41458604, 2025). "We also assessed [177Lu]Lu-DUNP19 uptake in the HCC1954 breast cancer model, characterized by high LRRC15 expression in stromal cells and LRRC15-null cancer cells." (PMID 41022704, 2025). "Our analysis revealed the function of LRRC15 enriched in the collagen metabolic process and cell adhesion signaling pathway in breast cancer, showing the importance of LRRC15 for the modulation of the BC microenvironment and tumoral progression." (PMID 38611080, 2024). "Recently, COL10A1 was identified as an overexpressed predictive biomarker for breast cancer coexpressed with LRRC15." (PMID 37287543, 2023). "In preclinical studies, the LRRC15-targeting antibody-drug conjugate ABBV-085 showed antitumor effect in breast cancer and ovarian cancer." (PMID 36744260, 2023). "The survival analysis in Kaplan–Meier plotter database confirmed that the up-regulation of LRRC15 were correlated with shorter OS of breast cancer patients, respectively." (PMID 32043519, 2020). "The co-expression profile of COL10A1 was identified with a large cluster of 19139 genes across 66 breast carcinomas, and LRRC15 is a correlated gene." (PMID 32043519, 2020). "Finally, we investigated the therapeutic efficacy of [177Lu]Lu-DUNP19 in the HCC1954 breast cancer model, composed of LRRC15- cancer cells supported by LRRC15+ stroma." (PMID 41022704, 2025). "Furthermore, LRRC15 was found to be overexpressed in aggressive cancer cells, such as breast cancer, ovarian cancer, and osteosarcoma." (PMID 36317112, 2022). "LRRC15 (leucine rich repeat containing 15) is a biomarker of myCAF in pancreatic and breast cancer." (PMID 35008832, 2021). "We unearthed that LRRC15 were significantly up-regulated in breast cancer tissues." (PMID 32043519, 2020). "COL10A1 could be considered as a predictive biomarker for prognosis of breast cancer with co-expressed LRRC15." (PMID 32043519, 2020). "In breast cancer, Leucine-rich repeat-containing (LRRC) protein 15 (LRRC15) has been identified as one of the significantly overexpressed genes in tumors that metastasize to the bone." (PMID 41458604, 2025). "Our LRRC15-RIT approach effectively targeted various cancer models, including models of breast cancer, osteosarcoma, glioblastoma, and colorectal cancer, all representing highly lethal cancers with distinct tumor biology and LRRC15 expression patterns." (PMID 41022704, 2025). "By comparing the COL10A1 and LRRC15 expression heat map derived from the UCSC Xena web-based tool, COL10A1 expression was proved to be positively related with LRRC15 transcript level, which was determined among a 50-gene qPCR assay (PAM50) breast cancer subtypes in TCGA database." (PMID 32043519, 2020).
sarcoma (11 papers, 2020 to 2025). A usually aggressive malignant neoplasm of the soft tissue or bone. "Of note, another molecule, the leucine-rich repeat containing protein (LRRC15), has become a promising anticancer agent due to its overexpression in both the stroma and tumor-associated fibroblasts (CAFs) of some tumors, such as sarcoma, glioblastoma, melanoma, BC, among others." (PMID 36982282, 2023). "LRRC15-antibody targeted drug conjugate ABBV-085 has been developed to target LRCC15+ stromal desmoplasia in sarcomas and carcinomas, including ovarian cancer." (PMID 41008788, 2025). "LRRC15 is highly expressed on stromal fibroblasts and tumor cells, such as those in melanoma, sarcoma, and glioblastoma." (PMID 38827307, 2024). "LRRC15 is expressed in many solid tumours and interstitial fibroblasts and is expressed on cancer cells directly from a set of mesenchymal origins (e.g., sarcoma, melanoma, and glioblastoma tumours)." (PMID 36653841, 2023). "LRRC15 sarcoma cell expression provided extra information to further refine the prognosis of patients besides histological grade which is considered the most significant predictor of outcome." (PMID 32210091, 2020). "ABBV-085, an antibody-drug conjugate targeting LRRC15, has shown promising results in sarcomas." (PMID 33567616, 2021). "Tumor-specific ADCs with LRRC15 expression, such as ABBV-085, are currently under testing in phase I clinical trials (NCT02565758) in sarcomas and other solid tumors, such as head and neck squamous cell carcinoma and BC." (PMID 36982282, 2023). "Leucine-rich repeat containing 15 (LRRC15), a member of the Leucine-Rich Repeat superfamily, is another target evaluated for ADC-based sarcoma therapy." (PMID 34440182, 2021). "On the non-FAP front, the ABBV-085 tested an LRRC15-directed antibody–drug conjugate in sarcomas and other stromal-rich cancers, with endpoints including pharmacokinetics, safety, and preliminary response." (PMID 41441395, 2025). "ABBV-085 specifically targets LRRC15, and this drug is currently undergoing a first-in-human phase I study (NCT02565758) for the treatment of sarcomas and other advanced solid tumors; the preliminary results demonstrate its effectiveness in terms of antitumor activity." (PMID 38611080, 2024). "Given the high significant expression of LRRC15 by sarcoma cells and its prognostic impact, we assessed the efficacy of ABBV-085, the first-in-class antibody–drug conjugate (ADC) directed against LRRC15, in several patient-derived xenograft models of UPS, LMS, and DDLPS." (PMID 32210091, 2020).
osteosarcoma (10 papers, 2022 to 2025). A usually aggressive malignant bone-forming mesenchymal neoplasm, predominantly affecting adolescents and young adults. "Elevated LRRC15 in stromal fibroblasts of multiple solid tumors, osteosarcoma, soft tissue sarcomas, and mesenchymal cancer cells are associated with higher tumor grades and worse outcomes in osteosarcoma and soft tissue sarcomas." (PMID 41228205, 2025). "For instance, LRRC15-targeting ADCs demonstrated enhanced efficacy in osteosarcoma cell lines with high LRRC15 expression." (PMID 41441395, 2025). "Tests of Cys fragments such as ADC have become more interesting as more data become available concerning the use of full IgG ABBV-05 ADCs anti-LRRC15 as a therapeutic agent for osteosarcoma." (PMID 36293532, 2022). "We further studied LRRC15-targeted RIT in a translationally relevant orthotopic osteosarcoma model." (PMID 41022704, 2025). "In osteosarcoma PDX models, LRRC15-monomethyl auristatin (MMAE) conjugates significantly decreased tumour volume compared to cisplatin alone." (PMID 40983796, 2025). "Tumor models with LRRC15+ cancer cells included K7M2LRRC15+, HuO9 and SAOS2 osteosarcomas (OS) and U118MG glioblastoma (GBM)." (PMID 41022704, 2025). "Given the high expression of LRRC15 on HuO9 osteosarcoma cells, we also sought to understand how the effects of [177Lu]Lu-DUNP19 therapy would change in a tumor of different tissue origin and with lower LRRC15 expression." (PMID 41022704, 2025). "Proteins that are overexpressed on osteosarcoma cells, such as the glycoprotein non-metastatic B (GPNMB), the leucine-rich repeat-containing 15 (LRRC15), B7-H3, GD2, and HER2, could represent potential targets for ADCs." (PMID 37109122, 2023). "In addition, osteosarcoma cell surficial receptors, such as glycoprotein nonmelanoma protein B (GPNMB, also known as osteoactivin), and leucine-rich repeat containing protein 15 (LRRC15), were also proven as promising targets with a few trials conducted." (PMID 37198232, 2023).
ovarian carcinoma (10 papers, 2020 to 2025). A malignant neoplasm originating from the surface ovarian epithelium. "On the website LinkedOmics, we analysed the genes most related to LRRC15 using data from 581 ovarian cancer patients from the TCGA database." (PMID 36653841, 2023). "A diagnostic ROC (receiver operating characteristic) curve was used to determine the diagnostic significance of LRRC15, PDPN and CD8 as three independent indicators for primary platinum-resistant ovarian cancer." (PMID 36653841, 2023). "Meanwhile, we observed that CD8 + T-cell infiltration decreased with increasing LRRC15 expression in the tissues of patients with advanced ovarian cancer." (PMID 36653841, 2023). "This suggested that LRRC15 + CAFs participate in the construction of an immunosuppressive microenvironment in ovarian cancer and promote immune escape." (PMID 36653841, 2023). "Only LRRC15 was consistently highly expressed in solid tumours of ovarian cancer and was related to pathological stage, original therapy outcome and overall survival (P < 0.05)." (PMID 36653841, 2023). "LRRC15 is indeed related to the primary resistance of ovarian cancer, and treatments targeting LRRC15 may reverse ovarian cancer primary resistance." (PMID 36653841, 2023). "Platinum resistance is a difficult problem in the first-line treatment of ovarian cancer; our results showed that it could also be predicted by the LRRC15 + CAF phenotype." (PMID 36653841, 2023). "Our results suggest that LRRC15 + CAFs in mesenchymal ovarian cancer may be used as a biological indicator to predict the proportion of patients who would likely respond to immunotherapy." (PMID 36653841, 2023). "Next, we identified LRRC15, LRRC32, and LRRC75A-AS1 as the three overexpressed gene signatures of the LRRC superfamily in ovarian cancer stroma." (PMID 36653841, 2023). "LRRC15, PDPN, and CD8 have certain accuracy as single biomarkers in predicting the outcomes of platinum-based chemotherapy for ovarian cancer." (PMID 36653841, 2023). "In summary, the expression of LRRC15 contributes to the proliferation of PDPN + CAFs and promotes the formation of mesenchymal ovarian cancer." (PMID 36653841, 2023). "Notably, LRRC15 has been shown to interact with β1-integrin, activating focal adhesion kinase (FAK) signaling and promoting ovarian cancer metastasis." (PMID 40388100, 2025). "However, the significance of LRRC15 as a stromal marker in the immune infiltration and primary platinum resistance of ovarian cancer has not been confirmed." (PMID 36653841, 2023).
glioblastoma (6 papers, 2019 to 2025). The most malignant astrocytic tumor (WHO grade IV). "The mechanism of tumor invasion and immune resistance involving COL6A3, COL1A1, COL1A2, LRRC15, IDO1, IL-6 and PTGS2 need to be further researched aiming to improve prognosis of aggressive glioblastoma." (PMID 33928021, 2021).